ENSG00000233656 (novel transcript)
Synonyms: LOC105374928; LOC105374929
Gene: Long non-coding RNA gene on chromosome 6 (11,414,636 to 11,516,515, forward strand). Ensembl gene ENSG00000233656.
Gene Ontology:
Molecular function: pre-mRNA 5'-splice site binding
Biological process: mRNA 5'-splice site recognition
Cellular component: U1 snRNP